CCR9 (C-C motif chemokine receptor 9)
Diseases named in the same sentence as CCR9 in open-access papers (continued):
Sharing a sentence is not in itself a finding about the gene and the disease.
infection (34 papers, 2012 to 2025). The state of being infected such as from the introduction of a foreign agent such as serum, vaccine, antigenic substance or organism. "Together, these data indicated that the two lines differed in the extent of CCR9 induction in Th2 effector cells, resulting in the delayed accumulation of Th2 cells at the site of infection in susceptible C57BL/6 mice." (PMID 39910093, 2025). "Focusing on the early stage of infection, we show here that both subsets comprise similar proportions of CCR9+ and/or α4β7+ cells." (PMID 39910093, 2025). "Higher RALDH activity (retinoic acid metabolism) in CD103+ MLN-DCs and an enhanced vitamin A metabolism during the early stage of infection resulted in higher CCR9+ T cells homing to the gut." (PMID 40092986, 2025). "In this study, we investigated theexpression of integrin α4β7 and CCR9 in CD4+ T cellsfollowing infection with PEDV." (PMID 40094365, 2025). "The results ofquantitative real-time PCR (qRT-PCR) indicated that the transcription ofintegrin α4β7 in CD4+ T cells was upregulated from 15to 45 min post-infection, and reached a peak at 30 min, while the transcriptionof CCR9 remained unaffected." (PMID 40094365, 2025). "In the current study, we investigated the surface expression of α4β7, CD11b and CCR9 in infection-induced PBs to better understand their migratory patterns in mucosal versus systemic compartments." (PMID 39512345, 2024). "We found that infection-induced PBs displayed significantly less CCR9 expression throughout the acute phase (hospitalization), while α4β7 was also downregulated at the early time point compared to PBs in the patient-matched recovered steady state." (PMID 39512345, 2024). "Clade Ib SARS-CoV-2 MA10 infection in CCR9−/− mice also developed more severe clinical disease including greater weight loss (P < 0.0001 to P < 0.05) and virus titers (P < 0.0005) than C57BL/6NJ mice." (PMID 35862771, 2022). "We found that relatively few MAIT cells expressed CCR2, CCR4, CCR6, CXCR3, CXCR4, and CCR9 in the lungs, spleen, thymus, and LP both before and after infection." (PMID 32849637, 2020). "Previous study reported that CCR9 is mainly function in IgA-ASCs migrating to the small intestine during infection with rotavirus." (PMID 30149800, 2018). "An increased expression of the CD11a integrin in naïve CD45RA+ T cells and overexpression of CCR5 and CCR9 during AVH-E infection have suggested an enhanced recruitment of these cells from periphery to the target tissue during the early phase of infection." (PMID 24963498, 2014). "CCR9-mediated gut homing of GATA-3+ cells is shown to correlate with high expression of aldehyde dehydrogenase (ALDH) in DCs isolated from the MLN of mice early during infection." (PMID 40092986, 2025). "Furthermore, Th2 and Th2/1 cells derived from MLN of untreated infection controls and IFN-γ treated mice displayed similar profiles of CCR9 and α4β7 expression on day 6 post infection." (PMID 39910093, 2025). "However, higher frequencies and cell numbers of intraepithelial Ly6A+CCR9+CD4+ T cells were infiltrated in small intestines from Trim29IEC-KO adult mice than those from Trim29fl/fl mice after EMCV infection for 3 days." (PMID 39396665, 2025). "In addition to directly damaging endothelial cells, cytokines also promote lung-derived CCR9+ CD4 + T cells to enter the small intestine through the circulation mediated by CCL25 to achieve lung-intestinal axis infection." (PMID 37323898, 2023). "In the miiuy croaker (Miichthysmiiuy), homologues for CCR3 and CCR9 have been isolated and expression analysis showed they were ubiquitously expressed in all tested tissues with their expression significantly upregulated after infection with V. anguillarum except that of CCR9 in the spleen." (PMID 26569324, 2015). "To determine whether RA signaling was directly targeted to CD4+ T cells during infection, we measured CCR9 expression by T cells as a surrogate marker of RA activity." (PMID 22927819, 2012).
infection (continued). "The accelerated small intestinal homing of type 2 cells seen in infected BALB/c compared to C57BL/6 mice correlated with the higher CCR9 expression by GATA-3+ cells and the higher ALDH activity of DC isolated from MLN of BALB/c mice early during infection." (PMID 39910093, 2025). "In contrast, the expression levels of CD186, CXCR5, CCR9, CCR10 and CD103 were unaffected by the infection." (PMID 36298634, 2022). "In up-regulated genes of head kidney samples, 2 genes respond to infection by D. pseudospathaceum-clone I (HYAL2, PRF1), 3 to clone XII (RGCC, CYP27B1, CCR9) and 6 to the clone mix treatment (ITGA5, SIX1, ATP1B3, MEF2C, MLF1, MYLPF)." (PMID 25254967, 2014). "Levels of mRNAs for CCL2, CCL3L1, CCL4, CXCL10, CCR1 and CCR5 were significantly increased in at least one time point following infection in two experiments and CCL5, CCR9 and CXCR4 mRNA were significantly increased in one of the experiments." (PMID 24083897, 2013). "Those mRNAs for CCL2, CCL31, CCL4, CXCL10, CCR1 and CCR5 were significantly increased following infection in both experiments in at least one time-point and CCL5, CCR9 and CXCR4 mRNA were significantly altered in one of the experiments." (PMID 24083897, 2013). "Fitting the age-dependent profile of CCR9 expression, CD11c+ DC derived from MLN of young BALB/c mice comprised significantly higher frequencies CD103+ALDH+ DC at day 6 post-infection compared to DC from older individuals of the same line as well as compared to DC from age-matched C57BL/6 mice." (PMID 39910093, 2025). "We find that during infection with the original Wuhan strain, plasmablasts in blood produce IgA1, IgG1, and IgM, and that most express CCR10 and integrin β1, only some integrin β7, while the majority lack CCR9." (PMID 37071584, 2023). "Furthermore, in addition to nonsynonymous differences in LZTFL1, CCR9, FYCO1, and SLC6A20A/B, regulatory differences were seen for genes in this locus at baseline as well as in the context of infection." (PMID 35862771, 2022). "Similarly, FoxP3+ CD8 T-cells expressing gut homing markers CCR9 and Integrin-β7 were also rapidly increased in acute and chronic ART- infection." (PMID 35967314, 2022). "Clinically affected cows demonstrated significantly higher numbers of CXCR3+ (Th1-type) and CCR9+ (total small intestinal lymphocytes) cells at the site of infection compared to the subclinical cows and noninfected controls." (PMID 33849661, 2021). "Strikingly, responding Ki67+ CD56bright NK cells expressed higher levels of CLA, CCR5, CXCR6, and CCR9 as compared to both non-responding NK cells during the acute phase of infection as well as healthy controls." (PMID 31467285, 2019). "Hence, the differential ALDH/RA profile of BALB/c DC compared to DC from aged-matched C57BL/6 mice complies with the distinct patterns of CCR9 expression and, consequently, recruitment of MLN-derived GATA-3+ cells to the small intestine upon infection with enteric nematodes." (PMID 39910093, 2025). "Flow cytometry analysis showed comparable frequencies and cell numbers of intraepithelial Ly6A+CCR9+CD4+ T cells in small intestines from Trim29fl/fl and Trim29IEC-KO adult mice before EMCV infection or from Trim29fl/fl and Trim29IEC-KO suckling mice before rotavirus infection." (PMID 39396665, 2025). "In summary, the findings of the current study indicate that clinically infected cows have higher numbers of CXCR3+ (Th1-type) and CCR9+ (total small intestinal T cells) cells at the site of infection when compared to subclinically infected and noninfected control cows." (PMID 33849661, 2021). "Thus, our findings suggest that infection-induced PBs are distinct from the typical mucosal PBs and, based on their low CCR9 expression, are not targeted to the small intestine but rather could migrate to the site of inflammation." (PMID 39512345, 2024).
infection (continued). "While basal expression of these receptors and integrins was comparable in all groups of uninfected mice, CCR9 and CX3CR1 were significantly upregulated on pDC after infection in WT but not in Tlr7−/y mice." (PMID 36278864, 2022). "In contrast to SARS-CoV MA15 infections, HKU3-SRBD MA virus titers on 4 dpi were not significantly different between CCR9−/− and wild-type mice, with all animals clearing infectious virus by 7 dpi." (PMID 35862771, 2022).
inflammation (7 papers, 2011 to 2025). Aberrant reaction of the microcirculation characterized by movement of fluid and leukocytes from the blood into extravascular tissues. "Our research uniquely addresses this gap by elucidating the interplay between gut leakage, cytokine spillover (e.g., IL-17), microbial translocation, and immune cell trafficking (via α4β7 and CCR9) in driving pulmonary inflammation." (PMID 40435188, 2025). "Conjunctival inflammation in acute forms of ocular allergy has increased CCR4+CCR9+ effector T cells, with a diminished frequency of CD4+CD25+FOXP3+ regulatory T cells in peripheral blood." (PMID 33114004, 2020). "Our first approach to analyse the regulatory role of CCR9 in allergic lung inflammation in vivo was to use a murine model of ovalbumin-induced airway inflammation." (PMID 27795621, 2016). "CCR9 knockout improves cardiac inflammation and fibrosis by inhibiting CCR9/CCL25 activation as well as inflammatory cytokines chemotaxis, which maintains electrical activity of cardiomyocytes and reduces the APD prolongation as well as the ion current disorder." (PMID 34712704, 2021). "These cells return to basal levels at 48 hours after stimulation, suggesting that these CCR9+ cells might be specifically important at very early phases of lung inflammation." (PMID 27795621, 2016). "Further, Ccr9–/– pDCs consistently migrated efficiently to livers with concanavalin A–induced inflammation, and exerted a more effective immunosuppressive effect, resulting in better protection against acute liver inflammation than that demonstrated by WT pDCs." (PMID 35943802, 2022). "Altogether these results suggest that expression of CCR9 is important for the recruitment of CD4+ T and possibly CD8+ T cells during allergen-induced airway inflammation." (PMID 27795621, 2016).
cardiovascular disease (3 papers, 2016 to 2024). "However, it has not been investigated whether CCR9 is involved in other cardiovascular diseases." (PMID 27585634, 2016).
Lung (3 papers, 2016 to 2025). "Flow cytometry revealed mis-homing of gut-primed immune cells (α4β7+ and CCR9 + CD4+) to the lungs and tracking bacteria via GFP- tagged fecal microbiome confirmed microbial translocation from the gut to the lungs which may contribute to lung inflammation." (PMID 40435188, 2025).
adenocarcinoma (2 papers, 2014 to 2025). A common cancer characterized by the presence of malignant glandular cells. "This disparity may arise from histology-specific modulation of downstream effectors: adenocarcinomas exhibit higher serum CCL25 levels, while CCR9-driven upregulation of VEGF, MMP-2, and MMP-9 promotes angiogenesis and metastatic dissemination." (PMID 40607416, 2025).
hematologic malignancies (1 paper, 2019). "Additionally, the development of improved monoclonal antibodies targeting molecules involved in the trafficking of MM, CLL, and ALL cells, such as CXCR4, CD44, SLAMF7/CS1, and CCR9 might open new opportunities for clinical treatments against these hematologic malignancies." (PMID 30787933, 2019).
CCR9 also shares sentences with these, for which no sentence is quoted: rheumatoid arthritis (6 papers); viral infection (5); allergic reaction (3); Hepatitis (3); lymphoma (3); allergies (2); multiple myeloma (2); small bowel Crohn disease (2); acute promyelocytic leukemia (1); allergic conjunctivitis (1); Anxiety (1); bladder cancer (1); cholangitis (1); chronic T cell leukemias (1); colon (1); colonic carcinoma in situ (1); colorectal adenocarcinoma (1); dengue (1); diffuse large B-cell lymphoma (1); enteropathy (1); enterovirus infection (1); fatty liver (1); fibrosis (1); glioblastoma (1); hairy cell leukemia (1); Hodgkins lymphoma (1); hyperlipidemia (1); Insulin resistance (1); liver cancer (1); lymph node metastasis (1).
A further 21 diseases each share a sentence with CCR9 in 1 paper.